PROX1 (prospero homeobox 1)
Diseases named in the same sentence as PROX1 in open-access papers (continued):
Sharing a sentence is not in itself a finding about the gene and the disease.
tumor (continued). "To examine whether the ability of Prox1 to inhibit tumor growth depends on breast tissue microenvironment or it is a general property of Prox1, we employed a heterotopic xenograft mouse model." (PMID 37508533, 2023). "Moreover, tumor-infiltrating macrophages from Prox1+/– mice showed increased M2 macrophages proportion compared to WT littermate controls." (PMID 35663931, 2022). "Moreover, IHC analysis reveals that the expression of PROX1 is more intense in the perineural infiltration areas and in tumor emboli than in the tumor itself." (PMID 35885529, 2022). "The relationship between PROX1 and cancer development is complex, and the functional role and mechanism of PROX1 in tumour progression are largely unknown." (PMID 36433955, 2022). "IHC analyses showed that the knockdown of PROX1 could significantly inhibit the expression of β-catenin and vimentin, but promoted the expression of E-cadherin in transplanted tumor tissues." (PMID 35342346, 2022). "PROX1 has been ascribed tumor suppressive and oncogenic properties in different cancer types." (PMID 35159256, 2022). "Therefore, we identified PROX1 as a critical factor for the LKB1-AMPK axis that mediates tumour metabolic plasticity to direct the therapeutic response to metformin." (PMID 36433955, 2022). "To address whether the alteration of PROX1 was involved in tumour metabolic flexibility, we examined the survival capacity of HCC cells following metabolic stress." (PMID 36433955, 2022). "These genetic alterations, which are widely considered to be responsible for the inactivation of tumor-suppressor genes, could explain the strongly reduced levels of PROX1 protein in carcinomas of the biliary tract." (PMID 35885529, 2022). "As expected, PROX1 depletion attenuated tumour cell death upon glucose starvation." (PMID 36433955, 2022). "Notably, PROX1 is reduced by glucose starvation or AMP-activated protein kinase (AMPK) activation and is elevated in liver kinase B1 (LKB1)-deficient tumours." (PMID 36433955, 2022). "In line with the immunofluorescence data, the absolute number and the relative frequency of medullary sinus macrophages (MSMs) tended to be reduced in tumor-draining LNs of Pdpnfl/fl × Prox1-CreERT2 mice, whereas the expression of costimulatory molecules by these macrophages was not altered." (PMID 35892863, 2022). "We therefore further investigated whether PROX1 rewired the therapeutic response of KL tumour to phenformin." (PMID 36433955, 2022). "Metformin also reduced the tumour weight of the PROX1-WT and PROX1-S79A groups." (PMID 36433955, 2022). "Interestingly, perineural and lymphatic invasion areas showed intense PROX1 staining and a high mRNA PROX1 amplification rate, implying an active role for PROX1 in tumor spread." (PMID 35885529, 2022). "Even though PROX1 has been demonstrated to play an important role in the development of human cancers, whether it exerts an oncogenic or a tumour suppressor function is complex and depends on cancer types." (PMID 36433955, 2022). "Congruently, the genes upregulated in tumor-draining LN fLECs, including several transcription factors that regulate lymphatic differentiation and lymphangiogenesis (Prox1, Klf4, Sox7, and Yap1), were significantly enriched for proliferation-, migration-, and angiogenesis-related GO terms." (PMID 35892863, 2022). "High PROX1 expression (>30% of the tumor cells) correlated with shorter overall survival (OS)." (PMID 35885529, 2022). "PROX1 is expressed in various human cancers and is speculated to play a crucial role in carcinogenesis and tumor spread." (PMID 35885529, 2022).
tumor (continued). "Nude mice bearing MDA-MB-231 xenograft tumors were used to investigate whether PROX1 could still promotes tumor proliferation and metastasis in vivo." (PMID 35342346, 2022). "Current research has shown that Prox1 is overexpressed in tumor tissues, such as kidney cancer and gastric cancer, while downregulated in tumor tissues, such as primary liver cancer, indicating that it may play different roles in different tumor tissues." (PMID 34183992, 2021). "Thus, PROX-1 seems to be involved in tumor progression by promoting cancer cell invasion and migration, but also in tumor metastasis through lymphangiogenesis regulation." (PMID 34638342, 2021). "Since Rho family proteins can regulate cytoskeleton and play a certain role in the adhesion, invasion, and migration of tumor cells, this study speculated whether Prox1 acted through Rho family proteins." (PMID 34183992, 2021). "Lambrechts and co-workers classified tumor endothelial cells in different clusters based on the marker genes identified; Lymphatic endothelial cells (PDPN+, PROX1+), tumor-derived blood endothelial cells (FLT1+, IGFBP3+, and SPRY1+), malignant, and non-malignant endothelial cells." (PMID 33763348, 2021). "Interestingly, Takahashi and collaborators demonstrated that the mRNA of Prox1, which can act as a tumour suppressor, experienced RNA-editing and loses tumour-suppressive functions in a subset of human cancers." (PMID 33265998, 2020). "However, two studies based on mouse tumor models suggest a role for PROX1 in cancer stem cell maintenance and metastatic outgrowth." (PMID 31451731, 2019). "Therefore, the T-to-NT ratio was calculated and as a result we observed higher expression of PROX1 in three tumor cases (case number: 42, 149 and 157), whereas FGF2 expression revealed opposite pattern." (PMID 31717665, 2019). "Therefore, in some cases PROX1 was reported to function as an oncogene whereas in some others as a tumour suppressor." (PMID 31060342, 2019). "PROX1 is expressed in KS tumours as shown in several publications." (PMID 29934628, 2018). "Our findings indicated that PROX1 exhibits tumor-progressive function in OSCC." (PMID 30115834, 2018). "In PTC, PROX1 has been shown to be inactivated through mRNA downregulation and cytoplasmic mislocalization, and this inactivation substantially promoted the malignant behavior of the tumor." (PMID 29371975, 2017). "Several studies have shown that PROX1 may play different roles in different types of cancer, functioning as an oncogene in some of them and as a tumor suppressor gene in some others, depending on the type of cells that undergo transformation into cancer cells." (PMID 29371975, 2017). "The level of miR-9 was higher in tumor tissues with high Prospero homeobox 1 (PROX1) has been shown topromote CRC progression)/low E-cadherin (which has a key role in cell adhesion) than that of tumor tissues with low PROX1/high E- cadherin." (PMID 28392501, 2017). "In addition, restoration of PROX1 impaired tumor formation and diminished invasiveness of PTC cells." (PMID 27411302, 2016). "In addition to its role in physiological development, PROX1 has been ascribed tumor suppressive as well as oncogenic effects in human cancers." (PMID 27626492, 2016). "PROX1 protein was localized in the nucleus of the tumor cells." (PMID 27626492, 2016). "Promoter hypermethylation may be a regulatory mechanism for PROX1 that is tumor type-specific, depending on cellular context and specific signaling pathways." (PMID 27626492, 2016). "Immunopositive tumor cells for the anti-PROX1 antibody were detected in all samples." (PMID 27626492, 2016). "PROX1 has been ascribed both oncogenic and tumour suppressive functions in human cancers." (PMID 21559010, 2011). "Currently, tumour grade is an important clinical indicator of prognosis in CRC and our study revealed that high PROX1 expression was associated with high tumour grade, but not with other clinicopathological parameters." (PMID 21970873, 2011).
tumor (continued). "The majority of the tumour samples expressed PROX1 (91%, 471 out of 517)." (PMID 21970873, 2011). "The majority of the tumour samples showed some degree of PROX1 expression (91%, 471 out of 517)." (PMID 21970873, 2011). "In addition, these results confirm the previous preclinical observations suggesting that PROX1 has a role in tumour progression in CRC." (PMID 21970873, 2011). "However, the prevailing location of Prox1 is diversified, which depend on different cell type of tumors, as well as differential stages of tumor." (PMID 23675176, 2010). "The focus of Prox1 in physiological condition has been shifted to tumor genesis." (PMID 23675176, 2010). "It suggests that Prox1 may facilitate cell proliferation and migration in tumor progression and metastasis." (PMID 23675176, 2010). "However, recent studies suggest that Prox1 is more likely to facilitate tumor formation and accelerate tumor progression." (PMID 23675176, 2010). "Notably, late Prox1 OE reduced GFP+ tumor nodules at the endpoint (219.5 versus 13.75 nodules) and significantly increased median survival from 17 to 36.5 days, suggesting that PROX1 blocks tumor progression." (PMID 39948437, 2025). "However, it is essential to note that some investigations have indicated that Prox1 overexpression in colorectal cancer may paradoxically facilitate tumor growth, heterogeneous proliferation, and malignant progression." (PMID 40909948, 2025). "Additionally, we demonstrated that PROX1 helps maintain neuronal fate and supports tumor growth." (PMID 39470735, 2024). "PROX1 expression was significantly upregulated in human CRC tissues and positively associated with the maximum standardized uptake value (SUVmax), a measure of tissue 18-fluoro-2-deoxy-D-glucose uptake and an indicator of glycolysis and tumor cell activity, in patients with CRC." (PMID 36594098, 2023). "Therefore, via this action, Prox1 may act as a tumor-inhibiting barrier in normal breast tissue and cells." (PMID 37508533, 2023). "Moreover, PROX1 positivity correlated with better prognoses in the following subgroups: males, patients aged <66 years, patients with an intestinal cancer type, and patients with a tumor size of <5 cm." (PMID 35885529, 2022). "However, PROX-1 is also expressed by normal breast ductal epithelial cells and tumor cells." (PMID 35054174, 2021). "However, it is well accepted that PROX1 may promote tumor progression by facilitating cancer cell migration, invasion, and metastasis through its role as a key organizer of the lymphatic system." (PMID 34199763, 2021). "Similarly to PROX1, the lower PROX1-AS1 expression is associated with a higher tendency to the longer survival time of THC patients, and a higher expression level of PROX1-AS1 is observed in lower stages of the tumor." (PMID 32370142, 2020). "However, the role of PROX1 in tumor progression, especially in angiogenesis remains controversial." (PMID 31717665, 2019). "The PROX1 protein expression influenced in vitro migratory and invasive capacities and cytoskeleton deregulation but did not affect other classic hallmark characteristics of tumour cells, such as proliferation, apoptosis or cell cycle." (PMID 31060342, 2019). "Interestingly, Prox1 may exert tumor suppressive or tumor promoting effect, depending on the tissue context." (PMID 29371975, 2017). "In order to determine whether Prox1 may affect the ability of tumor cells to invade through extracellular matrix, we measured cell migration in trans-well migration, wound-healing and Boyden chamber Matrigel invasion assays in FTC-133 depleted of Prox1 or overexpressing the protein." (PMID 29371975, 2017). "One could hypothesise that those tumours in the present study with a higher proportion of immunopositive cells represent a more advanced, less differentiated phenotype than their counterparts with relatively low PROX1 expression." (PMID 21559010, 2011).
tumor (continued). "Analysis of the prognostic significance of PROX1 using the Kaplan–Meier model showed that high PROX1 expression (>30% of the tumour cells) correlated with shorter overall survival, compared with lower PROX1 expression (10–30%, respectively, <10% of the tumour cells)." (PMID 21559010, 2011). "Moreover, the findings showing that PROX1 is overexpressed in the majority of CRCs and that it promotes neoplasia, tumour growth, and malignant progression suggest that PROX1 expression may be associated with the outcome of CRC patients." (PMID 21970873, 2011). "Notably, Prox1 is emerged as a good target to treat tumor metastasis fundamentally." (PMID 23675176, 2010). "Therefore, cell type and tissue microenvironment may be crucial for PROX1 to play the oncogenic versus tumor suppressive role and further studies will be necessary to better understand the role of PROX1 in KS tumor development." (PMID 20730087, 2010). "In contrast, Podoplanin or Prox-1 were not expressed by these tumor-associated macrophages (TAM)." (PMID 19759906, 2009). "Several key mRNAs in our model, such as PROX1 and ODF3B, are well‐established in tumour biology, further reinforcing the biological relevance of our prediction framework." (PMID 40673609, 2025). "Our results demonstrate, for the first time, that miR-224-3p is loaded into EVs mediated by hnRNPA1 and that exo-miR-224-3p promotes tumor lymphangiogenesis and LNM through the GSK3B/β-catenin/PROX1 pathway." (PMID 39866224, 2025). "Strikingly, Prox1 knockdown induced a shift from HCC toward CCA, forming glandular tumor structures expressing KRT19 and decreased HNF4 levels." (PMID 39948437, 2025). "In summary, our study provides novel insights into the differential expression of the transcription factor PROX1 across histological subtypes of NSCLC and its potential involvement in tumor differentiation and regional lymphatic dissemination." (PMID 40843762, 2025). "Notably, our results also indicate that PROX1, a transcription factor previously implicated in RMS growth, functions as an upstream regulator of cholesterol biosynthesis, further anchoring this metabolic pathway in the broader transcriptional network that sustains tumor survival." (PMID 41249736, 2025). "Consistent with low WNT signaling in RevCSCs, BLM tumor stem cells had decreased expression of WNT/stemness-related genes compared to Min tumors such as Axin2, Id2, Sox4, Wnt6, Wnt10a, Id3, Prox1, and Id1." (PMID 38893159, 2024). "Our findings indicated that higher expression of PROX1 and α-SMA in CRC tissue was positively correlated with tumor cell invasiveness and advanced TNM stage." (PMID 38244581, 2024). "Through IHC and immunofluorescence analyses, significant expressions of PROX1 and α-SMA were uncovered within the cancer cells’ tumor matrix and a strong correlation was observed between PROX1 and α-SMA expression in CRC." (PMID 38244581, 2024). "Our study elucidates the influential roles of PROX1 and α-SMA in the CRC tumor microenvironment, highlighting their potential as critical prognostic biomarkers and therapeutic targets." (PMID 38244581, 2024). "The observations that the vast majority of tumor emboli in Mary-X fall within lymphatic channels were confirmed by companion podoplanin, LYVE1, and Prox1 immunocytochemical studies." (PMID 39669476, 2024). "Dual immunofluorescence showed that PDGFR-β was expressed in both tumor cells (CK19+) and LECs (labeled by PDPN, LYVE-1 or PROX-1)." (PMID 37307823, 2024). "Our findings revealed that LV capillaries were predominantly localized at the tumor–stroma border and also expressed the bonafide markers VEGF Receptor 3 (VEGFR3) and the PROX1 transcription factor." (PMID 37686421, 2023).
tumor (continued). "We also performed IHC analysis of SW480 xenograft tumor tissues and confirmed that the protein levels of the glycolytic enzymes GLUT1, GLUT4, HK2, LDHA and LDHB were lower in xenografts from PROX1 knockdown cells than in those from control cells." (PMID 36594098, 2023). "Mechanistically, PROX1 can induce dephosphorylation of β-catenin and phosphorylation of ERK1/2, p38 and JNK to participate in tumor cell proliferation and lymphangiogenesis." (PMID 37803421, 2023). "Another stemness gene, PROX1, has been demonstrated to promote the proliferation of CRC stem cells and malignant tumor progression processes." (PMID 35958575, 2022). "Third, LKB1-AMPK axis-mediated PROX1 phosphorylation results in BCAA degradation, which suppresses mTOR signalling activity and facilitates tumour cell adaptation to metabolic stresses." (PMID 36433955, 2022). "Under pathological conditions, Prox1 promotes ISC survival through autophagy activation, thus facilitating tumor growth." (PMID 34414192, 2021). "Finally, we demonstrated that PROX1 and other vascular factors, such as VEGFC (vascular endothelial growth factor C), BAIAP2 (BAI1 associated protein 2), FGF2 (fibroblast growth factor 2), and PLAT (plasminogen activator) are differently expressed in FTC human tissues compared to non-tumor tissues." (PMID 31717665, 2019). "Taken together, these results indicate that PROX1 binds to the MMP14 promoter and thereby negatively regulates its expression in human tumour cells." (PMID 29934628, 2018). "Comparing with para-cancerous tissues, tumor tissues had significantly lower expression levels of LYVE–1 (P < 0.001) and VEGFR–3 (P = 0.013) and higher levels of Podoplanin (P = 0.016) and Prox–1 (P = 0.078)." (PMID 29162097, 2017). "PROX1 is upregulated in response to abnormally elevated oncogenic signaling of TCF/β-catenin in intestinal epithelium, important for tumor progression via disruption of cell polarity and adhesion." (PMID 29258163, 2017). "In summary, fucoidan inhibit tumor lymphangiogenesis and lymphatic metastasis by suppressing the NF-κB/PI3K/Akt signaling pathway through reduced levels of PROX1 and VEGFR3." (PMID 27203545, 2016). "In order to establish whether MSCs perform an important role in tumor metastasis, the present study treated MCF-7 and SGC-7901 cells with hBM-MSC-CM for 40 days, and then analyzed the expression of the lymphatic vessel-associated marker Prox-1 using western blot analysis." (PMID 25663886, 2015). "Tumor cells were visualized with anti-HLA-antibodies and lymphatic vessels with lymphatic endothelial cell (LEC)-specific anti-Prox1 antibodies (staining of LEC nuclei)." (PMID 24884418, 2014). "There was a significant difference in PROX1 amplification between OSCC and tumor-free margin samples (P < .001)." (PMID 25526434, 2014). "In this study, we analyzed the expression levels of PROX1 transcripts and proteins as well as PROX1 amplification and methylation status in OSCC tissues and tumor-free surgical margins." (PMID 25526434, 2014). "When stratified by tumor type, 30 (28.8%) ccRCC, 6 (85.7%) papillary RCC and 3 (75%) chromophobe RCC samples showed high PROX1 expression." (PMID 24797520, 2014). "These cases were studied by morphometry as well as IHC with tumor proliferation (Ki-67) and adhesion (E-cadherin) markers, myoepithelial (p63), as well as endothelial (podoplanin [D2-40], CD31, VEGFR-3, Prox-1) markers." (PMID 21297224, 2010). "We next stained KS biopsy sections with anti-PROX1 and LANA antibodies to analyze co-expression of PROX1 and LANA in KS tumor cells." (PMID 20730087, 2010). "Using EMSA, a significant binding was found to the MAZ-consensus site-containing the 5'-flanking sequences of the "Prox1-7902" transcript, in the cell nuclear extracts of HCC cell lines, of Mz-Cha2 cell line and of a HCC tumor sample." (PMID 18400094, 2008).